SLC22A3 (solute carrier family 22 member 3)
Description:
Electrogenic voltage-dependent uniporter that mediates the transport of a variety of organic cations such as endogenous bioactive amines, cationic drugs and xenobiotics. Cation cellular uptake or release is driven by the electrochemical potential, i.e. membrane potential and concentration gradient. Functions as a Na(+)- and Cl(-)-independent, bidirectional uniporter. Implicated in monoamine neurotransmitters uptake such as dopamine, adrenaline/epinephrine, noradrenaline/norepinephrine, histamine, serotonin and tyramine, thereby supporting a role in homeostatic regulation of aminergic neurotransmission in the brain. Transports dopaminergic neuromodulators cyclo(his-pro) and salsolinol with low efficiency. May be involved in the uptake and disposition of cationic compounds by renal clearance from the blood flow. May contribute to regulate the transport of cationic compounds in testis across the blood-testis-barrier (Probable). Mediates the transport of polyamine spermidine and putrescine (By similarity). Mediates the bidirectional transport of polyamine agmatine. Also transports guanidine. Mediates the transport of choline. May mediate intracellular transport of organic cations due to its localization on endomembranes, thereby contributing to amine metabolism and intracellular signaling (By similarity).
Synonyms: EMT; EMTH; OCT3
Tractability: Small molecule: a structure with a bound ligand is known; a high-quality ligand is known; it belongs to a druggable protein family. Antibody: UniProt places it where antibodies can reach, with high confidence; its Gene Ontology location is reachable by antibodies, with high confidence; UniProt predicts a signal peptide or a membrane-spanning region. PROTAC: its protein half-life has been measured; a small molecule that binds it is known.
Target class: SLC superfamily of solute carriers; Electrochemical transporter; SLC22 family of organic cation and anion transporters; Transporter
Gene: Protein-coding gene on chromosome 6 (160,348,373 to 160,452,577, forward strand). Ensembl gene ENSG00000146477.
Subcellular location: Cell membrane; Apical cell membrane; Basolateral cell membrane; Mitochondrion membrane; Endomembrane system; Nucleus membrane; Nucleus outer membrane
Subcellular location (Human Protein Atlas): Vesicles; Cytosol
Pathways (Reactome):
Drug ADME: Abacavir transmembrane transport
Transport of small molecules: SLC-mediated transport of organic cations
Gene Ontology:
Molecular function: choline transmembrane transporter activity; monoamine transmembrane transporter activity; neurotransmitter transmembrane transporter activity; protein binding; quaternary ammonium group transmembrane transporter activity; transmembrane transporter activity; spermidine transmembrane transporter activity
Biological process: choline transport; dopamine uptake; epinephrine uptake; histamine transport; histamine uptake; neurotransmitter transport; neurotransmitter uptake; norepinephrine uptake; quaternary ammonium group transport; serotonin uptake; transmembrane transport; xenobiotic transport; amine transport; purine-containing compound transmembrane transport; spermidine transport; transport across blood-brain barrier; organic hydroxy compound transport; spermidine transmembrane transport
Cellular component: apical plasma membrane; basolateral plasma membrane; plasma membrane; endomembrane system; membrane; mitochondrial membrane; nuclear membrane; nuclear outer membrane; basal plasma membrane; neuronal cell body; presynapse
Genetic constraint (gnomAD): Loss-of-function variants: 41 observed, 42.76 expected, observed/expected ratio (o/e) 0.96, 90% interval 0.75 to 1.24. The synonymous counts are far from expectation, so gnomAD's model fits this gene poorly and the ratio says little. Missense variants: 678 observed, 647.07 expected, observed/expected ratio (o/e) 1.05, 90% interval 0.98 to 1.12. Synonymous variants: 312 observed, 255.55 expected, observed/expected ratio (o/e) 1.22, 90% interval 1.11 to 1.34.
Homologues: Orthologues: chimpanzee SLC22A3 (99% identical), macaque SLC22A3 (98% identical), pig SLC22A3 (93% identical), dog SLC22A3 (92% identical), rabbit SLC22A3 (92% identical), mouse Slc22a3 (87% identical), rat Slc22a3 (87% identical), guinea pig SLC22A3 (67% identical), zebrafish si:dkey-166k12.1 (31% identical), zebrafish oatx (30% identical), Drosophila melanogaster Orct (30% identical), Caenorhabditis elegans oct-1 (29% identical), and 45 more. Paralogues in human: SLC22A2 (49% identical), SLC22A1 (48% identical), SLC22A6 (31% identical), SLC22A8 (30% identical), SLC22A12 (30% identical), SLC22A5 (30% identical), SLC22A10 (28% identical), SLC22A13 (28% identical), SLC22A4 (28% identical), SLC22A24 (28% identical), SLC22A7 (28% identical), SLC22A15 (27% identical), and 10 more.
Diseases named in the same sentence as SLC22A3 in open-access papers:
SLC22A3 is named in the same sentence as 57 diseases in open-access papers, as found by Europe PMC text mining. Sharing a sentence is not in itself a finding about the gene and the disease. The quoted sentences say what the papers report.
prostate carcinoma (12 papers, 2010 to 2025). A carcinoma that arises from epithelial cells of the prostate gland. "Our study provides novel insights into the regulatory mechanisms of the SNP rs9364554 and its association with drug efficacy in prostate cancer through regulating SLC22A3." (PMID 39858458, 2025). "SLC22A3, a membrane transporter, has been linked to SNP rs9364554 risk loci for drug efficacy in prostate cancer." (PMID 39858458, 2025). "Recent genome-wide association study (GWAS) studies have linked SLC22A3 to SNP rs9364554 risk loci for prostate cancer, colorectal cancer and other diseases." (PMID 39858458, 2025). "This suggests that lower levels of SLC22A3 are associated with more advanced stages of prostate cancer." (PMID 39858458, 2025). "The markers are located in the proximity of SLC22A3, a gene that has been implicated in prostate cancer pathogenesis." (PMID 29266682, 2018). "Interestingly, an eQTL at prostate cancer risk locus SLC22A3 (encoding polyamine transporter OCT-3) was recently reported, with the PC risk allele associated with lower levels of SLC22A3 in prostate tissues, and reduced viability in vitro." (PMID 27732966, 2016). "This study provides a novel mechanism by which prostate cancers undermine drug efficacy through the downregulation of SLC22A3 by FOXA1 competition with AR to bind to SNP rs9364554." (PMID 39858458, 2025). "Together, all these patients’ data indicate that SLC22A3 is progressively downregulated with prostate cancer malignancy." (PMID 39858458, 2025). "Taken together, these results suggest that in primary prostate cancer, SLC22A3 is upregulated in AR FL-expressing cells but diminished in ARV-expressing cells in a background of C allele SNP rs9364554." (PMID 39858458, 2025). "The hOCT3 gene, SLC22A3, was also identified as an important risk locus for prostate cancer, and was markedly under-expressed in aggressive prostate cancers." (PMID 37924453, 2023). "This study also revealed that hypermethylation of the SLC22A3 promoter region in prostate cancer was one of the important mechanisms for the reduced expression of this transporter." (PMID 37924453, 2023). "MT1G, MSMB, SLC22A3, COMP and KRT15 have also been associated with aggressive and/or poor clinical outcome in prostate cancer." (PMID 36661662, 2022). "To investigate the clinical relevance of SLC22A3 downregulation in prostate cancers, we knocked out SLC22A3 in the prostate cancer C4-2 cell line to assess drug sensitivity to two clinically used anti-prostate cancer drugs, Enzalutamide (AR inhibitor) and JQ1 (BRD4 inhibitor)." (PMID 39858458, 2025). "Moreover, our studies have first demonstrated that the low expression of SLC22A3 is related to drug resistance, indicating the predictable role of SNP rs9364554 in the drug efficacy of prostate cancer patients." (PMID 39858458, 2025). "However, in prostate cancer tissues, the C/T heterozygous genotype exhibits a higher SLC22A3 transcription level than homozygous genotypes (C/C, T/T), suggesting a complex, non-canonical regulatory mechanism at play in cancerous tissues." (PMID 39858458, 2025). "We also noted differences in the total expression of the SLC22A3 and CTBP2 genes in BPH compared with prostate cancer." (PMID 20569440, 2010). "CTBP2 and SLC22A3 mRNA levels were reduced by 27% and 50% in prostate cancer tissues compared with BPH tissues (4.2 [IQR 2.5] v/s 2.1[IQR 1.6]; P = 0.008 for CTBP2 and 0.48 [IQR 0.75] v/s 1.01 [IQR 1.42]; P = 0.015 for SLC22A3)." (PMID 20569440, 2010). "It is noteworthy that SLC22A3 knockout alone does not affect prostate cancer cell proliferation and survival, suggesting that SLC22A3 is more likely to affect prostate cancer progression via its effects on drug efficacy." (PMID 39858458, 2025).
colorectal cancer (11 papers, 2012 to 2024). A primary or metastatic malignant neoplasm that affects the colon or rectum. "In summary, this thorough evaluation of SLC22A3 as a prognostic biomarker in colorectal cancer, integrating risk factor analysis, ROC curves, and DCA, establishes a robust framework for assessing the predictive accuracy and clinical relevance of the nomogram." (PMID 39346905, 2024). "This study investigates the differential expression of the SLC22A3 gene in colorectal cancer (CRC) and its associated biological pathways, utilizing Gene Ontology (GO), Kyoto Encyclopedia of Genes and Genomes (KEGG), and Gene Set Enrichment Analysis (GSEA)." (PMID 39346905, 2024). "This comprehensive evaluation presents the prognostic significance of SLC22A3 expression in colorectal cancer (CRC), integrating risk factor analysis, receiver operating characteristic (ROC) curves, and decision curve analysis (DCA)." (PMID 39346905, 2024). "OCT3 SNPs have been related to the level of SLC22A3 mRNA and the risk of prostate, colorectal cancer and other diseases." (PMID 29659532, 2018). "This study provides a comprehensive examination of immune cell infiltration and its correlation with SLC22A3 expression in colorectal cancer (CRC), utilizing multiple sophisticated analytical approaches." (PMID 39346905, 2024). "This analysis presents a detailed examination of the prognostic value of SLC22A3 in colorectal cancer (CRC), using various statistical and visual tools to validate its clinical significance." (PMID 39346905, 2024). "The findings underscore the significance of SLC22A3 as a potential biomarker and therapeutic target in colorectal cancer." (PMID 39346905, 2024). "On the other hand, the organic transporter SLC22A3 (shared by T2D and PUD) is highly expressed in the liver and intestine and associated with colorectal cancer and T2D53,54." (PMID 38802514, 2024). "Overall, this comprehensive analysis underscores the significance of SLC22A3 as a prognostic biomarker in colorectal cancer, providing robust statistical evidence and practical tools for its application in personalized patient management." (PMID 39346905, 2024). "This study investigates the correlation between SLC22A3 expression and various gene sets in colorectal cancer (CRC), employing Pearson correlation heatmaps and referencing specific gene sets from the literature." (PMID 39346905, 2024). "Given these difference among East Asians, further work to understand variation in SLC22A3 and colorectal cancer is needed." (PMID 33976257, 2021). "It has been shown that SLC22A3 is involved in the uptake of cisplatin, and in head and neck or colorectal cancer upregulated SLC22A3 expression improved cisplatin uptake and survival of the patients." (PMID 32599841, 2020). "On the other hand, SLC22A3 overexpression promoted cell proliferation and stimulated migration and invasion of colorectal carcinoma cell line models, while repression of the expression reversed these effects." (PMID 31874997, 2019). "Thus, in colorectal cancer, an OCT3 variant located at 6q26-q27 (rs7758229; c.975 + 8374G>A in the non-coding region of SLC22A3), has been associated with distal tumors." (PMID 29659532, 2018).
type 2 diabetes mellitus (7 papers, 2017 to 2025). A type of diabetes mellitus that is characterized by insulin resistance or desensitization and increased blood glucose levels. "In our cross-sectional case–control study, we showed the association of the rs2048327 SLC22A3 gene polymorphism with diabetic retinopathy in a Slovenian cohort with type 2 diabetes mellitus." (PMID 37626799, 2023). "The objective of this study was to investigate the association between the polymorphisms of the SLC22A3 gene and the development of DR among patients with type 2 diabetes in the Slovenian population (Caucasians)." (PMID 37626799, 2023). "We showed the association of the rs2048327 SLC22A3 gene polymorphism with DR in a Slovenian cohort with type 2 diabetes mellitus, indicating its possible role as a genetic risk factor for the development of this diabetic complication." (PMID 37626799, 2023). "The objective of this study was to investigate the relationship between twenty-one single nucleotide polymorphisms (SNPs) in the SLC22A1, SLC22A2, and SLC22A3 genes and their effects on metformin pharmacogenetics in Jordanian patients diagnosed with type 2 diabetes mellitus." (PMID 30934600, 2019). "Finally, after adjusting for BMI and age at diabetes diagnosis using multinomial logistic regression, this study found a genetic association between glycemic control and all tested SNPs within SLC22A1, SLC22A2 and SLC22A3 genes." (PMID 30934600, 2019). "Therefore, our aim was to investigate whether DNA methylation and gene expression of SLC22A1, SLC22A3, and SLC47A1 are associated with diabetes medication in the human liver." (PMID 28947922, 2017). "We next examined if DNA methylation in the SLC22A1, SLC22A3, and SLC47A1 genes was different in the human liver according to diabetes medication." (PMID 28947922, 2017). "Furthermore, DNA methylation in six CpG sites annotated to SLC22A1, one CpG site annotated to SLC22A3 and six CpG sites annotated to SLC47A1 were significantly different with false discovery rate (FDR) less than 5% according to diabetes medication." (PMID 28947922, 2017). "However, while SLC22A1 and SLC47A1 had higher expression than SLC22A3, no expression differences were observed for any of the three metformin transporters according to diabetes medication." (PMID 28947922, 2017). "Lower average and promoter DNA methylation of SLC22A1, SLC22A3, and SLC47A1 was found in diabetic subjects receiving just metformin, compared to those who took insulin plus metformin or no diabetes medication." (PMID 28947922, 2017).
coronary artery disease (6 papers, 2017 to 2022). "Multiple human genetic studies have replicated associations of polymorphisms in SLC22A3 with coronary artery diseases including recent studies in knockout mice." (PMID 35089508, 2022). "Previous GWAS analyses showed that the variant of SLC22A3 gene is associated with coronary artery disease." (PMID 34143809, 2021). "In addition, the SLC22A3 (OCT3)-LPAL2-LPA gene cluster has been identified as a risk locus for coronary artery disease, implying its potential relationship to lipolysis." (PMID 30653498, 2019). "Additionally, a recent study reported that SLC22A3 polymorphisms might decrease the risk of coronary heart disease by against inflammatory response, which implied that the inflammation response may be affected by cg25313204 methylation on SLC22A3 in atherosclerosis." (PMID 35915606, 2022).
hepatocellular carcinoma (6 papers, 2012 to 2022). A malignant tumor that arises from hepatocytes. "Higher methylation and lower expression of SLC22A1 and SLC22A3 was observed in hepatocellular carcinoma and prostate tumor compared with matched normal samples." (PMID 36461046, 2022). "Higher methylation and lower expression of SLC22A1 and SLC22A3 was previously observed in hepatocellular carcinoma and prostate tumor compared with matched normal samples supporting that higher methylation in metformin transporter genes could be associated with disease." (PMID 28947922, 2017).
renal cell carcinoma (6 papers, 2012 to 2023). "Similarly, a recent study showed that SLC22A3 expression in renal cell carcinoma cell lines also enhanced sensitivity to chemotherapeutics such as melphalan, irinotecan, and vincristine." (PMID 29088791, 2017). "Moreover, SLC22A3 expression in renal cell carcinoma cell lines enhances the sensitivity towards chemotherapeutics as melphalan, irinotecan and vincristin." (PMID 22439694, 2012). "Conversely, in the renal cell carcinoma cell lines A498 and 7860, a highly significant expression of SLC22A3 (hOCT3) was detected by reverse transcription PCR and TaqMan real-time PCR." (PMID 24278698, 2012). "In renal cell carcinoma (RCC) and colon cancer cell lines exhibiting MDR and augmented ABCB1 expression, we have identified PITX2 as a contributor to chemotherapeutic drug resistance through transcriptional upregulation of ABCB1 as well as ABCC1, ABCG2, and the drug uptake transporter, SLC22A3." (PMID 35582031, 2021).
breast carcinoma (5 papers, 2017 to 2024). "SLC22A3 has been extensively studied in many tissues and tumor cell lines and has been found to be associated with breast cancer, bladder cancer, and lung cancer." (PMID 29088791, 2017). "In breast cancer cell lines, SLC22A1 was only expressed in MCF-7 and ZR-75-1 cells, while SLC22A3 was exclusively expressed in MDA-MB-231 cells." (PMID 35008681, 2021).
esophageal squamous cell carcinoma (5 papers, 2018 to 2025). Esophageal squamous cell carcinoma (ESCC) is a type of esophageal carcinoma (EC) that can affect any part of the esophagus, but is usually located in the upper or middle third. "While rs9364554 was found to be associated with a decreased SLC22A3 transcript abundance, and found to be down regulated in familial esophageal squamous cell carcinoma." (PMID 29560112, 2018). "For example, the adenosine-to-inosine (A-to-I) editing in familial esophageal squamous cell carcinoma has been described for SLC22A3." (PMID 40414875, 2025). "Interestingly, SLC22A3 expression plays a role in other esophageal disorders: downregulation of SLC22A3 was reported in patients with familial esophageal squamous cell cancer." (PMID 31891614, 2019).